IRS1 (insulin receptor substrate 1)
Diseases named in the same sentence as IRS1 in open-access papers (continued):
Sharing a sentence is not in itself a finding about the gene and the disease.
Obesity (continued). "In adipose tissue, elevated TST expression is protective against obesity and type 2 diabetes mellitus (T2DM), showing positive correlations with metabolic health markers such as insulin receptor substrate 1 (IRS1) and adiponectin." (PMID 40107018, 2025). "In obesity and T2D, the tyrosine phosphorylation of IRS-1 is inhibited, leading to altered IRS-1 signaling and subsequent skeletal muscle IR." (PMID 40006091, 2025). "Insulin receptor substrates 2 (IRS2) is the primary isoform of insulin receptor substrate expressed in ECs, dysregulation of IRS1/IRS2 contributes to the metabolic disorder, obesity and diabetes." (PMID 40443971, 2025). "Previous studies have shown that diet-induced obesity increases the expression and activation of PTP1B, which inhibits tyrosine phosphorylation of IR and IRS1, and these changes were mostly reversed by exercise." (PMID 37389126, 2023). "We also identified CpGs and genes with links to obesity (NTRK2, PSTPIP2, MBIP) and glucose and fat metabolism (IRS1)." (PMID 37649101, 2023). "Additionally, exercise is associated with the improvement of β-cell function, modulation of insulin receptor substrate 1 (IRS1) phosphorylation, lowering of ceramide plasma levels, and induction of angiogenesis, which are also mechanisms by which exercise improves overweight and obesity-induced IR." (PMID 37635963, 2023). "Research has demonstrated that adipocytes’ secretion of TNF-α can prompt the phosphorylation of IRS-1 serine and reduce GLUT-4 expression, resulting in disruptions in insulin-regulated glucose metabolism and the onset of obesity-related IR." (PMID 38045856, 2023). "Mechanistically, increased PA levels in plasma can induce liver PYCR1 expression to further inhibit the IRS-1/Akt/mTOR signalling pathway and thus exacerbate HFD-induced obesity and metabolic dysfunction." (PMID 36088469, 2022). "This is in accordance with a previous study where both forms of IRS1 were altered in the endometria from women with both obesity and PCOS compared with women with normal weight or with obesity." (PMID 35409282, 2022). "They reported that adipogenic and insulin signaling genes (CEBPB, PPARG, ADIPOQ, IRS-1, IRS-2, GLUT4, among others) were downregulated in obesity." (PMID 36432612, 2022). "Insulin-stimulated phosphorylations of INSR, IRS-1, Akt2, and GSK3β were markedly reduced in the liver of HFD-fed mice, indicating that HFD-induced obesity impaired hepatic insulin signaling." (PMID 35328400, 2022). "The major intracellular stress kinase that links TNFα to inhibitory serine phosphorylation of IRS-1 in T2DM and obesity is the c-Jun N-terminal kinase (JNK) family of MAPK." (PMID 34070553, 2021). "Studies have proved that high level of BCAAs in plasma can continuously activate the mTOR signaling pathway and disassociate insulin receptor from insulin receptor substrate 1, which is closely related to the occurrence of T2DM and obesity." (PMID 34149613, 2021). "In obesity, IR is demonstrated by the downregulation of IRS2 and persistent expression of IRS1, and inflammatory cytokines including TNF-α downregulate IRS2 mRNA expression." (PMID 34135978, 2021). "Several of the observed DMCs were located in genes related to T2D or obesity, such as ALOX12, PAMR1, and GNAS in WB; IRS1, LEP, and ADIPOQ in SAT; LCAT, FOXA2, KCNQ1, and GCKR in VAT; and PKD4, HNF4A, XBP1, and PON1 in LT." (PMID 29466957, 2018). "This study revealed pleiotropic protective effects of DPP-4 inhibitor SIT on cardiac function, glycemia, and β-cell function together with reducing S6K1 activation and IRS-1 and IRS-2 degradation in the obesity female mouse model." (PMID 30116740, 2018). "Moreover, there are some data showing that obesity could also cause ER stress, which, in turn, results in inhibition of insulin receptor signaling through hyperactivation of JNK and subsequent serine phosphorylation of insulin receptor substrate-1." (PMID 27983710, 2016).
Obesity (continued). "TNF-α produced by obesity-induced inflammation stimulates IKK41, JNK42, and mTOR/S6K43, 44, which enhance serine phosphorylation of insulin receptor substrate-1 (IRS-1)." (PMID 26316333, 2015). "Obesity and inflammatory cytokines increase ubiquitin ligase SOCS1/3 and MG53, thereby decreasing IRS-1/2 levels." (PMID 26074875, 2015). "For example, the development of obesity and insulin signaling in type 2 diabetes is influenced by the PMDS as insulin receptor substrate 1 is inactivated by degradation through this system." (PMID 25414638, 2014). "MCR1/CD68 ratio increased significantly after weight loss in parallel to adipogenic genes, such as FASN, ADIPOQ, IRS1 and SLC2A4, whereas LEP (an obesity gene marker) and IL6 (an inflammatory marker) decreased." (PMID 23951013, 2013). "In obesity, tyrosine phosphorylation of IRS-1 is inhibited by c-Jun N-terminal protein kinase (JNK)-dependent serine phosphorylation of IRS-1." (PMID 24454515, 2013). "In obesity, ER stress promotes the IRE1-JNK-dependent serine phosphorylation of IRS-1, which in turn inhibits the insulin receptor-induced tyrosine phosphorylation of IRS-1." (PMID 24705207, 2013). "Our results therefore uncouple the adipogenic, lipogenic, and obesity-inducing activities of p/CIP and SRC-1 as PPARγ coactivators from their activities on insulin signaling through IRS1." (PMID 22859932, 2012). "In obesity and IR, adipokine profiles are altered, with molecules such as CTRP3 (which enhances insulin sensitivity via AMPK activation) and WISP1 (which impairs insulin signaling through IRS-1 phosphorylation) playing opposing roles." (PMID 40426647, 2025). "Moreover, Cr supplementation increased the p-IRS-1, GLUT2, and GLUT4 expression in the liver of various animal models of metabolic disorders, such as NAFLD, obesity, T2DM and metabolic syndrome, and thus lowering the hepatic TG levels of these models." (PMID 38721033, 2024). "However, in the course of metabolic diseases related to obesity, both elevated cytokines (e.g., TNFα) and free fatty acid (FFA) trigger serine phosphorylation of IRS-1 by stress kinases, resulting in the development of insulin resistance." (PMID 34070553, 2021). "Along with these data, similar results were observed in MYPT1 phosphorylation as an indicator for ROCK activity and IRS1 serine 632/635 phosphorylation, which are ROCK’s phosphorylated sites (i.e., obesity decreased these parameters, but exercise increased them)." (PMID 34234788, 2021). "The mechanisms by which IL-1β mediates insulin-resistance have been attributed, at least in part, to downregulation of insulin substrate receptor-1 (IRS-1) and aberrant activity of the transcription factors NF-κB and FOXO1 (Forkhead box protein O1) during obesity or inflammatory conditions." (PMID 33178196, 2020). "Additionally, previous studies have reported that obesity from a HFD decreases the activity of the hippocampal insulin signaling pathway, including the activity of IRS-1, PI3K, p-PDK1, p-AKT, and p-GSK-3β." (PMID 31311133, 2019). "In maternal diet-induced obesity of offspring and IR in later life, miR-126 plays a negative role via targeting IRS-1." (PMID 27763497, 2016). "Thus, IRS1 and IRS2 together with IGFs and IGFRs have been involved in obesity, birth weight, diabetes mellitus, insulin sensitivity and cancer, showing the genetic associations of their polymorphisms." (PMID 27483248, 2016). "Our hypothesis was that trans-fatty acids might induce more severe obesity, IR and hepatic steatosis in comparison with a high fat diet through regulating DGAT1, ATGL and ACSL1, and IRS1 dependent pathways." (PMID 27248994, 2016). "The top-20 scoring GDAs from DisGeNET are very well-studied gene-disease relationships, like Alzheimer Disease and APP [amyloid beta (A4) precursor protein], obesity and MC4R (melanocortin 4 receptor), and Type 2 Diabetes Mellitus and IRS1 (insulin receptor substrate 1)." (PMID 25877637, 2015).
Obesity (continued). "The associations of 23 SNPs located within 17 candidate genes (MTHFR, PPARγ, LPL, INSIG, TCF7L2, FTO, KCNJ11, JAZF1, CDKN2A/B, ADIPOQ, WFS1, CDKAL1, IGF2BP2, KCNQ1, MTNR1B, IRS1, ACE) with overweight and obesity, diabetes, metabolic phenotypes, and MetS were examined in both studies." (PMID 24959828, 2014). "On the other hand, increases in muscle ceramide may contribute to impairments in muscle IRS-1/PI3K and Akt activation in obesity and diabetes." (PMID 26237474, 2014). "However as obesity advances and T2DM develops in response to a reversible or irreversible downturn in insulin secretion, the activation of hepatic IRS-1/PI3K, and thus of hepatic Akt, diminishes." (PMID 26237474, 2014). "As the most marked effect of maternal diet-induced obesity was on IRS-1 protein expression without changes at the mRNA level, we chose to examine mechanisms underlying this effect in further detail focusing on the potential role of miRNAs." (PMID 24749062, 2014). "In diet-induced obesity, overactivation of mTOR-S6K signaling favors expansion of the WAT mass, leading to insulin resistance of adipocytes through elevated serine phosphorylation of IRS1." (PMID 24391749, 2013). "Insulin-stimulated IRS1 (Tyr632) phosphorylation increased with resveratrol treatment in lean subjects but not in subjects with severe obesity (1.9 ± 0.2 vs. 1.3 ± 0.1 fold increase over the noninsulin, nonresveratrol-treated condition, for lean vs. severely obese, respectively, P < 0.05)." (PMID 38324260, 2024). "Importantly, in endometrial cells under hyperandrogenic and hyperinsulinemic conditions, TNFα increases the inactive form of IRS1, suggesting that a PCOS environment induces different alterations of p-IRS1 compared with the obesity condition in this in vitro model." (PMID 35409282, 2022). "Moreover, there have been no previous studies of IRS1 gene polymorphisms among T2DM patients in Ukraine, be it with only T2DM, or comorbid with obesity or CP." (PMID 35221617, 2021). "In addition, obesity-induced activation of JNK, mediated mainly by ER stress, promotes phosphorylation of insulin receptor substrate 1 (IRS-1) at serine sites that negatively regulate normal signaling through the insulin receptor/IRS-1 axis." (PMID 33668426, 2021). "Thus, when obesity, free fatty acids, and high glucose upregulate TBP-2 expression, this progress inhibits the expression of several insulin signaling-related genes, such as insulin receptor substrate-1 (IRS-1), and Akt phosphorylation." (PMID 29854083, 2018). "To confirm that the loss of IRS-1 was not driven by increased degradation, we applied a translational block in primary preadipocytes by treating with cycloheximide and showed that rate of IRS-1 decay was not affected by maternal diet-induced obesity." (PMID 24749062, 2014). "3-month old SERT−/− mice did not display obesity and hepatic steatosis (data not shown), but their IRS1 and AKT responses to insulin stimulation were reduced, further indicating that SERT−/− mice develop insulin resistance prior to a significant increase in the adiposity." (PMID 22412882, 2012). "Resveratrol further increased IRS1, Akt, and TBC1D4 insulin-stimulated phosphorylation and SIRT1 content in myotubes from lean women, but not in women with severe obesity." (PMID 38324260, 2024). "Two-way ANOVA showed a main effect of postnatal HFD treatment (p < 0.05), indicating an increase in the level of pIRS1 (i.e., decreased IRS-1 downstream signaling), but not for maternal HFD/obesity in pIRS1 levels." (PMID 32408716, 2020). "In the present study, resveratrol improved insulin-mediated signal transduction [insulin-stimulated phosphorylation of IRS1 (Tyr632), Akt (Ser473), and TBC1D4 (Thr642)] in the myotubes from lean individuals, but not in the myotubes from individuals with severe obesity." (PMID 38324260, 2024).
Obesity (continued). "Interestingly induction of Ser/Thr phosphorylation of IRS1 by insulin was similar in both the control and T2DM volunteers, suggesting that obesity-induced IR did not affect this aspect of insulin action." (PMID 23468892, 2013).
diabetes (225 papers, 2004 to 2025). "Patient P4, adolescent with diabetes, carrying a heterozygous mutation (c.193C>A:p.P65T) in the IRS1 gene." (PMID 41614819, 2025). "It has been reported that there is association between increased TNF-α levels in diabetes and impaired insulin signaling possibly by increasing IRS-1 serine phosphorylation." (PMID 37089941, 2023). "Nine diabetes-associated genes that had direct interactions with ten HLHS candidates were responsible for this enrichment, including the novel interaction of the diabetes-associated IRS1 with the HLHS candidate NRDC." (PMID 35456433, 2022). "In diabetes, the genes associated with lipid and glucose metabolism, such as PPARγ, IRS1 and IRS2 were genetic risk factors, and hepatic glutaminase mRNA was abundant during diabetes." (PMID 33466498, 2021). "Third, the precise molecular mechanism underlying the influence of IRS1 p.His713Tyr on the development of diabetes remains to be determined in further prospective studies." (PMID 32411229, 2020). "HCV is also considered to cause diabetes by proteasome ubiquitination of insulin receptor substrates 1 and 2 (IRS1/2), by effecting insulin signaling pathways or immune-mediated stress plays." (PMID 33520544, 2020). "A likely pathogenic rare missense heterozygous mutation in diabetes genes (c.2137C > T, p.His713Tyr in IRS1) was identified, which was a cosegregate in this family and not in nonrelated healthy controls." (PMID 32411229, 2020). "The insulin signaling pathway consisted of IRS-1/PI3K-Akt signaling which is a major mechanism underlying the development of diabetes." (PMID 32655424, 2020). "IRS-1 polymorphism has been found related to insulin resistance, obesity and type 2 diabetes mellitus." (PMID 33335512, 2020). "Intriguingly, IRS-2-deficient mice are more susceptible to diabetes than IRS-1 knockout mice because of the impairment of insulin secretion, indicating that IRS-2 contributes to the molecular basis for diabetes." (PMID 32610588, 2020). "We have previously reported that diabetes-induced increases in tumor necrosis factor alpha (TNFα) can cause phosphorylation of insulin receptor substrate 1 (IRS-1) on serine 307, thus inhibiting normal insulin signal transduction in retinal endothelial cells." (PMID 32432228, 2020). "The aims of this study were to evaluate the presence of the IRS-1 Arg972 polymorphism in pregnant women with diabetes or mild gestational hyperglycemia, and in their newborns." (PMID 25859280, 2015). "In mice, deletion of Irs1 is associated with profound growth retardation and increased longevity whereas Irs2-deficiency causes diabetes and female infertility." (PMID 23741292, 2013). "In that vein, chronic inflammation, increased free fatty acids, and elevated oxidative stress associated with diabetes inhibit insulin signaling by increasing serine phosphorylation of IRS1 in muscle and adipose tissue." (PMID 21754917, 2011). "IRS1 (insulin receptor substrate-1) is an important gene associated with diabetes because it is a substrate for insulin receptor tyrosine kinase and plays a crucial role in insulin signaling, insulin-like growth factor-1 signaling and regulates insulin secretion by β cells in the pancreas." (PMID 36292779, 2022). "Diabetes patients have insulin signal transduction pathway changes or defects, which are associated with lower levels of the molecules of insulin signaling such as “Insulin receptor substrate-1 (IRS-1) and phosphatidylinositol 3-kinase PI3K”." (PMID 36160451, 2022). "A previous study indicated that an abnormal IR/IRS-1 signaling in the hippocampus was closely related to the cognitive disorder caused by diabetes, while the PI3K/AKT signal in the hippocampus could also regulate emotional impairment." (PMID 34149862, 2021). "The IR/IRS-1 signaling pathway was recognized as an association between diabetes and depression." (PMID 34149862, 2021).
diabetes (continued). "To investigate whether the alteration of IRS1 through Ser phosphorylation is associated with type 1 diabetes mellitus (T1DM)-induced memory deficits, we generated STZ-induced insulin-deficient T1DM mice." (PMID 31426549, 2019). "This could be of relevance in the pathogenesis of diabetes and other endocrine disorders; however, whether rs6725556 is indeed a functional polymorphism affecting IRS1 expression needs to be proven in future functional studies." (PMID 21917432, 2012). "However, even with increased expression of MG53 in the heart, the expression of IRS-1 protein in the αMHC-MG53 mouse heart remained higher than in WT littermates, which is contrary to the conclusion that MG53 functions as an E3-ligase to degrade IRS-1 causing the development of diabetes." (PMID 34183055, 2021). "Cerebellum is known to be the origin of the tremor and diabetes induces the PD pathology in the cerebellar Purkinje cells in vivo, which may be responsible for the association between altered p-IRS-1 in blood NDEVs with the severity of tremor." (PMID 33344443, 2020). "IRS1 p.His713Tyr is implicated as a possible pathogenic mutation in monogenic diabetes, which might require further validation, and the precise molecular mechanism underlying the influence of IRS1 p.His713Tyr on the development of diabetes remains to be determined in the further prospective studies." (PMID 32411229, 2020). "Besides hyperglycemia and increased endogenous thrombin generation, insulin receptor substrate-1 polymorphisms may be responsible for high on-treatment platelet reactivity in diabetes." (PMID 30268122, 2018). "Biomarkers for other diseases, such as p‐serine‐312‐IRS1 and p‐pan‐tyrosine‐IRS1 for diabetes mellitus (DM), can also be used for the diagnosis of AD." (PMID 40503760, 2025). "Our results align with previous studies in rodents indicating that TRIM72 is sufficient to promote diabetes through IRS1 downregulation, a finding supported by human data showing elevated TRIM72 and blood glucose following oral glucose administration." (PMID 41000062, 2025). "A reduction in IRS‐1 levels is considered a major contributor to the development of catabolic diseases including diabetes." (PMID 41000062, 2025). "The hyperactivation of insulin receptor substrate 1 (IRS-1), an important upstream regulator of mTOR, has also been linked to diabetes." (PMID 39770519, 2024). "The results revealed a contrasting pattern, with reduced NEDD8 expression in patients with type 2 diabetes mellitus, accompanied by an induction of IRS1 and IRS2 expression levels." (PMID 38272982, 2024). "Previous studies reported a significant lowering of IRS1 mRNA in non-insulin-dependent diabetes mellitus (NIDDM) individuals and in adipose tissue of abdominally obese women." (PMID 37447192, 2023). "This intervention resulted in a notable reduction in hippocampal serine phosphorylation of insuline receptor substrate-1 (IRS-1), an event frequently observed in both diabetes and AD." (PMID 38201258, 2023). "The mRNA expression levels of insulin signaling-related factors such as Ir, Irs1, Akt, and Glut4 declined in adipose tissues in the case of type 2 diabetes mellitus." (PMID 36902049, 2023). "Multiple cellular studies have reported that activated ERK1/2 in diabetes induces IRS1 serine phosphorylation, which inhibits IRS1 tyrosine phosphorylation." (PMID 36119080, 2022). "Among the pathways identified are PI3K- signaling pathway, Ras signaling pathway, type 1 diabetes mellitus, Insulin receptor substrate 1 related pathway, and regulation of insulin-like growth factor." (PMID 36451736, 2022). "Healthy fertile subjects had 23.82 timeshigher expression of the INSR gene than the fertile oneswith diabetes (P<0.0001, 95% CI: 2.207-4.293) and13.83 times higher IRS-1 gene (P<0.0001, 95% CI:0.679-1.813)." (PMID 36273315, 2022).